U3 (Small nucleolar RNA U3 )
Synonyms: LOC124901506
Gene: Small nucleolar RNA gene on chromosome 6 (28,015,568 to 28,015,777, forward strand). Ensembl gene ENSG00000199851.
Gene Ontology:
Biological process: RNA processing
Cellular component: nucleolus
Homologues: Orthologues: chimpanzee U3 (99% identical). Paralogues in human: SNORD3P1 (78% identical), SNORD3G (77% identical), U3 (77% identical), U3 (76% identical), U3 (75% identical), SNORD3D (75% identical), U3 (74% identical), SNORD3E (74% identical), U3 (73% identical), U3 (72% identical), SNORD3H (71% identical), U3 (71% identical), and 12 more.